STAT3 (signal transducer and activator of transcription 3)
Diseases named in the same sentence as STAT3 in open-access papers (continued):
Sharing a sentence is not in itself a finding about the gene and the disease.
tumor (continued). "The reactive state of tumor-associated astrocytes is driven by the JAK/STAT3 pathway and increased proliferation." (PMID 31186414, 2019). "It is well established that chronic activation/phosphorylation of STAT3 is associated with cellular transformation and tumor progression, including cellular proliferation and cellular migration and invasion." (PMID 31695609, 2019). "Persistently activated STAT3 is a promising target for a new class of anticancer drug development and cancer therapy, as it is associated with tumor initiation, progression, malignancy, drug resistance, cancer stem cell properties, and recurrence." (PMID 31684051, 2019). "Loading STAT3 siRNA on lipid-substituted PEI is associated with decreased viability and proliferation of tumor cells by upregulation of caspase-3 and IL-6, and down-regulation of STAT3 and VEGF." (PMID 31569687, 2019). "In cancer patients, IL-6 induces development and immunosuppressive function of MDSCs and tumor-associated macrophages through signal transducer and activator of transcription 3 (STAT3)-mediated mechanism." (PMID 31013891, 2019). "As an important member of the STAT family of transcription factors, STAT3 is linked to malignant transformation and tumor progression." (PMID 30674340, 2019). "Here we demonstrate that miR-34a exerted tumor-suppressive effects in HGSC by regulating the IL-6R/STAT3 signaling pathway and the associated expression of Snail, MMP9, CDK4, and survivin." (PMID 31448054, 2019). "The overall effect of STAT3 stimulation in T cells is generally correlated with a poor cytotoxic/increased regulatory response and as such, is associated with a defective anti-tumor immune response." (PMID 31766350, 2019). "Elevated STAT3 phosphorylation in ovarian cancer is associated with paclitaxel resistance and increased tumor cell invasion post-therapy, consistent with the elevated expression of mesenchymal/CSC genes and increased tumor initiating potential." (PMID 31684144, 2019). "Mechanistically, YTHDF2 inhibited STAT3 phosphorylation and tumor growth by degrading IL11 mRNA, which encodes the dominant IL-6 family cytokine that endows gastrointestinal cancers with proliferative and invasive capacity." (PMID 31735169, 2019). "This group were also the first to report that STAT3 is persistently activated in immune cells associated to a tumor, which leads to the suppression of innate and adaptive immune responses." (PMID 31388334, 2019). "It was stated that loss of SHP2 protein sustains tumor growth by promoting JAK/STAT3 pathway activation." (PMID 31500143, 2019). "Peripheral and tumor-associated NK cells from STAT3-targeted tumor-bearing mice expressed elevated levels of NK activation markers NKG2D, CD69, Fas ligand (FasL) granzyme B, perforin, and IFNγ, resulting in reduced tumor growth and enhanced survival." (PMID 31057536, 2019). "Taken together, we concluded that blocking of STAT3 phosphorylation by AG-490 reduces osteolysis and tumor growth caused by BoM-1833 cell injection in athymic mice." (PMID 31040267, 2019). "The expression of PD-L1 is associated with a poor prognosis and inhibition of PD-L1 expression (e.g., through STAT3 or its partner inhibition) is associated to a decrease in cell proliferation and/or an increase in tumor cell death in most of these studies." (PMID 31480382, 2019). "STAT3 is also activated in infiltrating immune cells including tumor-associated macrophages (TAM) amplifying immune suppression." (PMID 31766350, 2019). "We analyzed STAT3 activity in tumor cells to understand mechanisms underlying the anti-tumor activity of MVP." (PMID 31092229, 2019). "In contrast, we demonstrate that inhibition of stromal TGFβR2 reduces IL‐6 production from cancer‐associated fibroblasts, resulting in a reduction of STAT3 activation in tumor cells and reversion of the immunosuppressive landscape." (PMID 31609088, 2019).
tumor (continued). "Nuclear TRIM59 then promotes the tumor-suppressive histone variant macroH2A1 ubiquitination and degradation, leading to enhanced STAT3 signaling activation and tumorigenicity." (PMID 31488827, 2019). "Cytokine receptor-induced signaling sustains and amplifies the activation of STAT3, NF-κB and AP-1 in a positive amplification loop, fueling tumor-associated inflammation." (PMID 31766350, 2019). "STAT3 activation in the tumor stroma has been associated with an impaired tumor immune surveillance of both NK and CD8+ T cells." (PMID 31781102, 2019). "Downstream genes activated by STAT3 have been associated with tumor proliferation and survival, including PIM1/PIM2, MYC, BIRC5 and BCL2L134–39." (PMID 30741931, 2019). "These signaling pathways, including the mTOR, NF-κB, AKT, and STAT3 pathways, are generally associated with tumor cell proliferation and survival." (PMID 30927928, 2019). "We found pacritinib treatment suppressed cell viability and colony/tumor sphere formation in association with decreased expression of STAT3, Sox2, PDCD4, and miR-21-5p and increased GFAP expression." (PMID 31269723, 2019). "Embelin, a potent, nonpeptidic cell-permeable inhibitor of X-linked inhibitor of apoptosis protein (XIAP), exerts anti-tumor effects by limiting IL-6/STAT3 activation and the Th17 immune response in GBs." (PMID 31698775, 2019). "CXCR2 deficiency increased SAP18 expression in tumor-bearing mice, which reduced STAT3 phosphorylation through restraining ERK1/2 activation." (PMID 31395859, 2019). "The activation of STAT3 has been linked to tumor development, primarily via its anti-apoptotic effects, immune escape, promotion of angiogenesis and poor prognosis." (PMID 30123088, 2018). "In breast cancer, for example, the enrichment of JAK2 and STAT3 mutations in distant metastases relative to the primary tumor suggests their involvement in facilitating tumor progression and dissemination." (PMID 30041675, 2018). "IL-6 has been linked with malignancy across a number of different tumour types, with its importance being related to downstream signalling via STAT3 activation." (PMID 29256156, 2018). "Constitutive STAT3 activation in cancer cells has been associated with enhanced transcription of anti-apoptotic genes, thus increasing tumor resistance to apoptosis and promoting neoplastic progression." (PMID 30149591, 2018). "In particular, the autocrine/paracrine IL-6/JAK/STAT3 feed-forward loop has been implicated as a key player of tumor progression and metastasis." (PMID 29934528, 2018). "STAT3 expression was significantly increased in tumor tissues compared to the adjacent normal tissues, and higher STAT3 expression in tumors was associated with shorter interval of survival of GBM patients." (PMID 29774125, 2018). "Aberrant STAT3 activation in HCC tumor tissue is associated with proliferation, metastasis and invasion." (PMID 29558404, 2018). "Our findings suggest G3BP1 as a novel mediator of RCC tumor progression and further extends the current knowledge about IL-6/STAT3 associated mechanism in RCC carcinogenesis." (PMID 29717134, 2018). "STAT3 is believed to be associated with tumor growth because it is steadily activated in tumor cells." (PMID 29707119, 2018). "Activated STAT3 has been reported to prevent tumor cell apoptosis by regulating associated genes, such as Bcl-2, Bcl-xL and Fas." (PMID 30594131, 2018). "It would be interesting to compare tumor development in animals lacking specific IL-20 cytokines or individual receptor chains to STAT3-deficient animals to elucidate the contribution of single members of the IL-20 cytokine family to tumor formation." (PMID 29967613, 2018). "These new tolerogenic activities of tumor-associated myeloid cells are controlled by an oncogenic transcription factor, signal transducer and activator of transcription 3 (STAT3)." (PMID 29921770, 2018).
tumor (continued). "STAT3 activation in a variety of tumor-associated myeloid cells generates a powerful and multilayered backing for cancer progression and immune evasion." (PMID 29921770, 2018). "In particular, STAT3 activities were shown to be either pro-oncogenic or tumor-suppressive according to the tumor etiology/mutational landscape, suggesting that the molecular bases underlining its functions are still incompletely understood." (PMID 30231553, 2018). "In this regard, pharmacological or genetic inhibition of hypoxia-induced autophagy decreased STAT3 phosphorylation in hypoxic tumor cells and restored tumor cell susceptibility to CTL-mediated lysis." (PMID 30622432, 2018). "While not statistically significant, metformin exposure was associated with a trend toward decreased tumor size, and analysis of tumor tissues demonstrated decreased expression of STAT3 and its targets." (PMID 30211120, 2018). "Kuo and collaborators showed that a suicide gene therapy targeting the STAT3/ NFκB pathways in a TNBC cell line resulted in a reduction of tumor growth, loss of invasiveness and an enhanced sensitization of the TNBC cell line to cisplatin therapy." (PMID 29928478, 2018). "In the mouse tumors, high levels of nuclear p-STAT3 were observed at the tumor edge in association with both tumor cells and stromal cells." (PMID 29963254, 2018). "It showed that the STAT3 score, nuclear STAT3 score, pathological stage (≥ pT3), lymph node involvement, lymphovascular invasion, and tumor grade were associated with both progression-free survival and cancer-specific survival." (PMID 30091994, 2018). "Constitutive activation of STAT3 is also a feature of many human malignancies including cervical, and head and neck cancers, and is associated with a poor prognosis in various tumours." (PMID 29630659, 2018). "In the subgroup of high grade tumor, STAT3 and nuclear STAT3 were significantly associated with both progression-free survival and cancer-specific survival in univariate analysis but not in multivariate analysis." (PMID 30091994, 2018). "STAT3 and p-STAT3 are significantly associated with tumor development, migration, and incursion in cancer through angiogenesis and lymph-angiogenesis." (PMID 29560131, 2018). "HIC-1 plays a important role in the physiological regulation of multidrug resistance through the IL-6/STAT3 signal pathway, and has been implicated in the other various tumor." (PMID 30202238, 2018). "Yet another lncRNA, lncSox4, highly expressed in HCC tumors and CD133+ TICs, has been shown to promote self-renewal and tumor-initiating ability through association with STAT3 and upregulation of Sox4." (PMID 30477236, 2018). "STAT3 activation has also been reported to be associated with the progression of tumor aggressiveness." (PMID 30104473, 2018). "Cooperate with tumor-associated macrophages (TAMs), TINs can produce IL-6 and granulocyte colony-stimulating factor, activate the STAT3 signaling pathway to slow down neutrophil degranulation and enhance tumor proliferation." (PMID 30103707, 2018). "HNSCC is associated with suppressed expression of GPRC5A, which is positively associated with tumor grade, along with the activation of STAT3." (PMID 30417009, 2018). "The Stat3 pathway is tightly associated with tumour invasion, metastasis, and angiogenesis in cancers." (PMID 30297887, 2018). "As shown in Pten phosphatase-deficient cancer cells, STAT3 can acquire an unexpected role as a tumor suppressor." (PMID 29921770, 2018). "The function of STAT3 can be either oncogene or tumor suppressor depending on the mutation status of cancer cells." (PMID 29844447, 2018). "Enhanced cell growth and tumour progression as a result of LIF pathway activation has been linked to downstream activation of the JAK/STAT3 and Akt/mTOR pathways." (PMID 30263091, 2018). "Blocking STAT3 in tumor-associated myeloid cells can permit development of antitumor immune responses, at the same time eliminating tumor resistance to therapeutic assaults." (PMID 29921770, 2018).
tumor (continued). "Tumor-associated myeloid cells and STAT3 signaling in this compartment are now commonly recognized as an attractive cellular target for improving efficacy of standard therapies and immunotherapies." (PMID 29921770, 2018). "miR-17-5p and miR-20a are two other important modulators of STAT3 expression, downregulated in MDSCs by tumor associated factors." (PMID 29419779, 2018). "In line with this evidence, expression of representative IL-6-mediated STAT3 target genes such as Socs3 and Timp1 were largely unaltered in tumor livers of lean IL-6Rα-deficient mice compared to controls." (PMID 30224299, 2018). "For example, it has been reported that STAT3 activation via gp130 in enterocytes is associated with cell survival signaling and cell cycle progression in the tumor microenvironment." (PMID 29867925, 2018). "The use of beta-blockers can reduce the risk of tumor metastasis by inhibiting the release of catecholamines and the activity of signal transducer and activator of transcription-3 (STAT-3), resulting in reduced NK cell activity inhibition and angiogenesis." (PMID 29805965, 2018). "IL-6 in particular activates STAT3 signaling in tumor cells and high STAT3 phosphorylation is associated with a poor prognosis in many types of cancers." (PMID 29883385, 2018). "In the subgroup of advanced tumor (≥pT1), only high STAT3 tumor had a significantly higher risk of both disease progression (p = 0.002) and cancer-specific mortality (p = 0.003)." (PMID 30091994, 2018). "As a signaling hub onto which many oncogenic signals converge, STAT3 represents an attractive potential target to render tumor cells susceptible to growth inhibition or apoptosis." (PMID 29686295, 2018). "In response to various cytokines, phosphorylated (active) Stat3 serves as a transcription factor, promotes antitumor responses, and promotes development and recruitment of tumor-associated macrophages and MDSCs." (PMID 29762501, 2018). "Conjugation of an anti–CTLA-4 aptamer to a STAT3 siRNA helped to overcome this limitation and achieved STAT3 gene silencing in both tumor-associated T cells and tumor cells." (PMID 29865257, 2018). "Tumor exosomes have been shown to activate MDSCs by inducing autocrine IL-6 production, which is further linked to STAT3 activation and response to chemotherapy." (PMID 30383833, 2018). "To get mechanistic insight, we analyzed sex‐specific STAT1 effects on tumor parameters, STAT3 activation, and expression of STAT1 target genes implicated in tumorigenesis." (PMID 29419930, 2018). "Epithelial Stat3 deletion results in intriguing sex-associated discrepancies; K-ras mutant tumors are decreased in female LR/Stat3Δ/Δ mice whereas tumor burdens are increased in males." (PMID 30389925, 2018). "The transcription factor STAT3 is known to cause IL10-mediated suppression of both STAT1 as well as STAT1-mediated induction of the anti-tumor cytokine IL12." (PMID 30041669, 2018). "In particular, recent findings have demonstrated that the differentiation of tumor-associated macrophages (TAMs) from monocytic precursors at tumor sites is controlled by downregulation of the activity of the STAT3 transcription factor induced by cancer cells." (PMID 29662647, 2018). "Signal transducer and activator of transcription 3 (STAT3) is frequently activated in OC, being associated with the tumour formation and chemoresistance of OC." (PMID 29966369, 2018). "In the subgroup of advanced (≥pT1) tumor, STAT3 and pSTAT3 were significantly associated with both progression-free survival and cancer-specific survival in univariate analysis." (PMID 30091994, 2018). "STAT3 physically interacts and functionally cooperates with NF-κB in tumor cells and also in tumor-associated immune cells." (PMID 29588647, 2018). "IL-6 trans-signaling results in strong phosphorylated STAT3 expression and a significantly increase tumor-associated antigens carcinoembryonic antigen-related cell adhesion molecule 5/6 (CEACAM5/6) expression." (PMID 28725043, 2017).
tumor (continued). "Based on emerging evidence, constitutive STAT3 activation in human malignancies is associated with tumour cell proliferation, survival and angiogenesis." (PMID 28423603, 2017). "We suggest that selective loss of pY239/240-ShcA signalling dampens STAT3 immunosuppressive signals and renders tumour cells sensitive to immune checkpoint inhibitors and tumour vaccines." (PMID 28276425, 2017). "Loss of GRIM-19 reduces tumor cells respiration supporting the importance of impaired STAT3 serine translocation into the mitochondria." (PMID 27966451, 2017). "in the form of a siRNA-aptamer chimera to target tumor-associated CD8+ T cells to silence STAT3 and activate tumor-specific T cells." (PMID 28325295, 2017). "Specifically, activation of either NF-κB, STAT3, or Smad3 signaling has been associated with cancer-induced muscle mitochondria dysfunction in tumor-bearing mice." (PMID 28785374, 2017). "Persistently activated STAT3 plays an important role in photocarcinogenesis through upregulation of genes involved in tumor-associated inflammation, anti-apoptosis and proliferation." (PMID 28912452, 2017). "IL-6, a major trigger of the signal transducers and activators of transcription 3 (STAT3) signaling pathway, have been implicated in regulation of tumor growth and metastasis of BCa." (PMID 29190997, 2017). "Collectively, it is suggested that IL-6 is a critical tumor promoter in colitis-associated cancer and STAT3 is essential for the transduction of tumor-promoting signals from IL-6." (PMID 28852270, 2017). "Confirming known functional tumor-associated genes in stromal cells such as Stat3 and the proof that the found altered Ttl indeed is another tumor-suppressor gene in TAFs supports the strength of this assumption." (PMID 29228606, 2017). "A higher Stat3 activation in tumor cells is associated with lower survival rates of patients with several malignant tumors." (PMID 28415725, 2017). "In cancers, including TNBC, STAT3 is constitutively activated and frequently associated with poor prognosis and tumor resistance to anticancer therapy." (PMID 28084011, 2017). "To explore the mechanism underlying the role of CAFs on tumor metastasis, we investigated the effect of CAFs on IL-6/STAT3 signaling pathway." (PMID 29100297, 2017). "It has been widely accepted that the accumulation of MDSC is driven by tumor-derived inflammatory cytokines and associated signaling pathway, notable IL-6 and its downstream STAT3 signal." (PMID 29100353, 2017). "A previous study demonstrated that JAK2/STAT3 was also associated with the development of tumor cachexia by inducing a systemic inflammatory response." (PMID 28489606, 2017). "STAT3 negatively regulates NK activation and tumor cell killing, as STAT3‐deficient NK cells generally exhibit enhanced cytolytic activity and cytokine secretion in vitro and in vivo." (PMID 28695716, 2017). "Since STAT3 expression is linked to neo-angiogenesis, we characterized more fully the effect of miR-223-3p on tumor vasculature." (PMID 28915663, 2017). "Decreased levels of both phospho-STAT3 and NF-κB in tumor tissues were also confirmed by enzyme-linked immunosorbent assay (ELISA)." (PMID 28460481, 2017). "Mounting evidence has shown that Stat3 is strongly linked to tumor angiogenesis and metastasis and is related to poor prognosis in different tumors." (PMID 28415725, 2017). "The ability of combinations to synergistically inhibit tumor growth was linked to synergistic changes in glutamine metabolism, the associated modulation of STAT3/Src, mTORC1 and AMPK signaling, and induction of apoptosis." (PMID 29202102, 2017). "Signal transducer and activator of transcription 3 (STAT3) is constitutively activated and overexpressed in many primary tumors, and is closely associated with tumor proliferation, angiogenesis, and immune escape." (PMID 29115974, 2017).